BRCA1 (BRCA1 DNA repair associated)
Diseases named in the same sentence as BRCA1 in open-access papers (continued):
Sharing a sentence is not in itself a finding about the gene and the disease.
gynecological cancers (36 papers, 2012 to 2026). "We have identified a high burden of pathogenic variants in several gynecologic cancer-related genes in the Slovenian population, most importantly in the BRCA1 gene." (PMID 37002323, 2023). "Yet, only a few previous studies have examined the population burden of gynecologic cancer predisposition genes beyond BRCA1/2 and Lynch syndrome genes in national cohorts." (PMID 37002323, 2023). "Recently, poly (ADP-ribose) polymerase (PARP) inhibitors (PARPis) have been clinically approved for breast and gynecological cancer patients, significantly improving their quality of life, especially of patients with BRCA1/2 mutations." (PMID 36091750, 2022). "Among prospectively detected BC or gynecological cancer phenocopies in the path_BRCA1/2 families, we found that 4/48 have pathogenic variants in high-penetrance cancer genes: two BC- and one CRC-associated gene (ATM, BRCA2 and MSH6, respectively)." (PMID 29371908, 2018). "A total of 619 women with BRCA1 gene mutation, ovarian, endometrial, metastatic, other gynecological cancers, or benign gynecological diseases were included." (PMID 28182133, 2017). "Furthermore, we identified several loss-of-function mutations of USP4 in human gynecological cancers, the catalytic activity of which or their interaction with BRCA1 is disrupted." (PMID 38734703, 2024). "Only the patient with BRCA1 mutation had a family history of gynecologic cancer with unknown origin." (PMID 34048176, 2021). "BRCA1/2 genes mutations may be contributed to the relationship between having a family history of gynecological cancer and digestive system cancer and increased risk of hormone receptor negative breast cancer." (PMID 25212775, 2014). "Importantly, BRCA1/2 genes mutations have been detected in gynecological cancer and digestive system cancer." (PMID 25212775, 2014). "Consistent with a chronic inflammatory state, VEGF signaling and VEGFA expression were upregulated in HRD tumors, expanding prior findings in BRCA1-deficient murine ovarian models to a broader spectrum of HRD and gynecological cancers 9,87." (PMID 41279139, 2025). "Due to the pronounced role of BRCA1 and BRCA2 in hereditary breast and ovarian cancer, different mutations and variants of BARD1 were first investigated in breast cancers and various gynecological cancers in the late 1990s and early 2000s." (PMID 32708251, 2020). "BRCA1, a tumor suppressor gene, plays an important role in gynecologic cancers, especially ovarian cancer." (PMID 29895933, 2018). "In conclusion, this study demonstrates the safety of single‐agent venadaparib for the treatment of patients with and without BRCA1/2 mutations in gynecologic cancers." (PMID 39945311, 2025). "The role of an FH of EOC as a predictor of EOC risk is already demonstrated, especially among BRCA1 mutation carriers; this is highly relevant considering that EOC is the third most common gynecologic cancer and has the worst prognosis and the highest mortality rate." (PMID 36307994, 2022). "We will then describe different variations of BARD1 present in non-breast and non-gynecological cancers, which are not driven by mutations in either BRCA1 or BRCA2 genes." (PMID 32708251, 2020). "Women with BC or gynecological cancer who had tested negative for path_BRCA1 or path_BRCA2 variants were included." (PMID 29371908, 2018).
male breast carcinoma (35 papers, 2004 to 2026). A malignant neoplasm involving the male breast. "Although BRCA2 is the most clearly associated gene, BRCA1 mutation is also considered in familial and even sporadic cases of male breast cancer." (PMID 27478808, 2016). "The association of ampullary cancers with male breast cancer may be related to BRCA1/2 mutations which are found in this cancer." (PMID 35454845, 2022). "Inherited mutations in BRCA1, and, mainly, BRCA2 genes are associated with increased risk of male breast cancer (MBC)." (PMID 30564557, 2018). "BRCA1 and, more commonly, BRCA2 mutations are associated with increased risk of male breast cancer (MBC)." (PMID 26857456, 2016). "Several risk factors including advancing age, positive family history and mutations in susceptibility genes such as BRCA1 and especially BRCA2 are considered for the study of male breast cancer." (PMID 27478808, 2016). "Nevertheless, identified BRCA1/2-positive male individuals benefit from early screenings for cancers such as prostate and male breast cancer, and their female relatives may benefit from cascade screening." (PMID 39320887, 2024). "Even though male breast cancer (MBC) risk encompasses both genetic and environmental aetiologies, the primary risk factor is a germline pathogenic variant (PV) or likely pathogenic variant (LPV) in BRCA2, BRCA1 and/or PALB2 genes." (PMID 37762649, 2023). "BRCA1, along with the BRCA2 gene which is more prevalent in male breast cancer, is a tumor suppressor that helps repair DNA double-strand breaks and decrease the amount of rapid cancerous growth in cells." (PMID 38137912, 2023). "Male breast cancer was absent in the BRCA1 c.676delT pedigrees, but was recorded for the BRCA2 c.7806-2A > G in 7 out 18 (39 %) families." (PMID 26852130, 2016). "Specifically, individuals with positive family history (especially those who are BRCA1/BRCA2 mutation negative), patients with bilateral disease, and patients with a family history of male breast cancer had a higher occurrence of 1100delC variants as compared with control individuals." (PMID 15535844, 2004).
sarcoma (35 papers, 2008 to 2025). A usually aggressive malignant neoplasm of the soft tissue or bone. "BRCA1/2 mutations are well‐known causes of HRD, 4 and 22% of sarcoma patients carry mutations in BRCA1 and BRCA2, respectively." (PMID 36779660, 2023). "Despite the fact that only 4% of sarcoma carry mutations in BRCA1, the best characterized HRR pathway gene, we found several other alterations, most in the form of amplifications and losses, in essential and associated members of the HRR pathway, particularly in UPS, MFS, LMS, ULMS, DDLPS and MPNST." (PMID 36779660, 2023). "In one family with 5382insC BRCA1 gene mutation, 2 cases with sarcoma were reported." (PMID 18783588, 2008). "A prior study found that the expression of PARP1, γH2AX, BRCA1, and BRCA2 was associated with shorter survival of patients with sarcoma." (PMID 40563612, 2025). "Studies with molecularly predicated therapies have yielded favorable responses to targeted treatments such as Trabectedin in relapsed sarcoma patients with favorable BRCA1 haplotypes." (PMID 40243416, 2025). "Therefore, the development of sarcoma in the patient may be associated with BRCA1 5382insC." (PMID 37047678, 2023). "A very low ΔTMB was found after trabectedin and olaparib both in BRCA1/2-proficient and -defective cell lines, and in sarcoma xenografts, ruling out a mutagenic effect of the drug combination." (PMID 34944915, 2021). "Indeed, a recent review about sarcomas highlights how specific signatures, such as TMB (Tumor Mutational Burden), MSI (Microsatellite Instability) and deficiency, in BRCA1/2 genes could be useful biomarkers in this type of tumor." (PMID 39769419, 2024). "No HRR mutations were detected in LGSOC, sarcoma, and borderline serous tumors in this study; 2.7% (4/46) BRCA1 and 1.2% (1/46) other HRR variants were reported in LGSOC in the GOG 218 study, and RAD54L was recently reported in one of six LGSOC in a Japanese study." (PMID 35186721, 2022). "A recent study investigated the molecular profiling of ped/AYA sarcomas and noted alterations in several DDR genes, including SLFN11, EWSR1, BRCA1, BRCA2, and MLH1." (PMID 40563612, 2025). "BRCA1, RAD51D, and additionally XRCC2 were downregulated in the M6 high-grade sarcoma, whereas XRCC3 was highly overexpressed." (PMID 35978432, 2022). "We employed immunohistochemistry (IHC) to measure PARP1, BRCA1, and RAD51 expression in a panel of 54 patient-derived sarcoma specimens." (PMID 28454547, 2017). "Immunohistochemistry score of intensity for PARP1, BRCA1, and RAD51 protein expression in formalin-fixed paraffin-embedded sarcoma samples." (PMID 28454547, 2017). "In striking contrast to BRCA1, BRCA2 alterations were found in 22% sarcoma." (PMID 36779660, 2023).
hereditary ovarian cancer (34 papers, 1998 to 2025). "Malignant transformation in BRCA-related familial ovarian cancer is thought to occur when the remaining wild-type allele undergoes pathogenic mutation or epigenetic silencing, thereby leaving only the germline BRCA1/2 mutant allele." (PMID 29464354, 2018). "We performed a molecular characterization of a novel BRCA1 synonymous variant discovered in a family with hereditary ovarian cancer (HOC) syndrome." (PMID 29760936, 2018). "Promoter hypermethylation was shown to cause loss of BRCA1 expression both in sporadic ovarian cancer and in hereditary ovarian carcinomas." (PMID 25986046, 2015). "High-grade serous carcinoma is the pre-dominant histotype associated with hereditary ovarian cancer and women with inherited mutations in BRCA1 have a lifetime risk of 40–60%." (PMID 25594072, 2014). "Hereditary ovarian cancer comprises 10 to 15% of all cases of ovarian malignancies and is mainly associated with germline mutations in the BRCA1 and BRCA2 genes." (PMID 23344037, 2013). "Moreover, germline mutations of BRCA1 have also been discovered, and it is reported that, for patients of familial ovarian cancer, over 80% of patients carry BRCA1 (or BRCA2) mutation." (PMID 33937409, 2021). "This system is composed of BRCA1/2 proteins (FANCS and FANCD1, respectively), whose mutations have been associated with breast and ovarian familial cancer development." (PMID 35159370, 2022). "The gene test of this patient showed mutations of uncertain significance in FANCA, BRCA1, and BRIP1, which have been associated with hereditary ovarian cancers." (PMID 34941061, 2021). "Germline loss-of-function (LOF) monoallelic mutations in genes involved in HR repair such as BRCA1, BRCA2, RAD51C, RAD51D and BRIP1 are associated with an increased risk of developing familial ovarian cancer." (PMID 29464354, 2018). "Restoration of BRCA1 and BRCA2 mediates resistance to platinum chemotherapy in recurrent BRCA1 and BRCA2 mutated hereditary ovarian carcinomas." (PMID 19602291, 2009). "While germline mutations in BRCA1 and BRCA2 predispose to hereditary ovarian carcinoma, somatic mutations in these genes are rare in sporadic ovarian carcinomas." (PMID 19602291, 2009). "The role of BRCA-1 and -2 are most often investigated in the context of hereditary ovarian cancer, but recent reports also highlight the relatively high prevalence of somatic mutations in BRCA-1 and -2 genes and the potential use of individualized therapy for these patients." (PMID 24281100, 2010). "The BRCA1 and BRCA2 gene status undisputedly plays a key role in genome integrity and hereditary ovarian cancer pathogenesis; however, the frequency and precise prognostic role of BRCA mutations at different locations of the genes remains largely unknown." (PMID 34898566, 2021).
Anxiety (33 papers, 2010 to 2025). Intense feelings of nervousness, tension, or panic often arise in response to interpersonal stresses. "The aim of this study was to compare the effect of RRM and IBS on quality of life, anxiety, and depression in women carriers of P/LP variants in BRCA1/2 genes who are followed in a High-Risk Breast Clinic in a Portuguese Breast Centre." (PMID 40445415, 2025). "Genetic counselling is provided to people who meet the criteria for BRCA1/2 testing because it is linked to reduced anxiety and cancer concerns, as well as enhanced accuracy regarding perceived risk in the short term." (PMID 39812114, 2025). "The aim of this study was to evaluate the mediating role of psychophysical stress in the relationship of anxiety and depression with quality of life and well-being in women undergoing genetic counseling for BRCA1/2 mutations." (PMID 39518053, 2024). "Anxiety is an important component for clinicians to consider when counselling women with BRCA1/2 pathogenic variants on preventative measures for BC." (PMID 36536421, 2022). "In this prospective cohort study we investigated the effect of anxiety, personality factors and coping styles on the decision-making process on risk management options in women with pathogenic variants in BRCA1/2." (PMID 36536421, 2022). "Commonalities existed with several COVID-19-related experiences predicting increases in anxiety and depression symptomologies among women with BRCA1/2 mutations." (PMID 34969949, 2021). "The current study provides a unique view in beginning to understand the impact of the COVID-19 pandemic on anxiety and depression among women with BRCA1/2 mutations." (PMID 34969949, 2021). "Apart from cardiology field, initial anxiety was identified as a risk factor for distress after BRCA1/2 genetic testing." (PMID 32384747, 2020). "A prior study reported that the percentage of BRCA1/2 or HNPCC genetic susceptibility testing recipients exhibiting an elevated level of anxiety dropped from 29.3% at two weeks to 14.1% at six months after disclosure of the results." (PMID 20537192, 2010). "However, increased rates of clinical anxiety have previously been reported for newly found BRCA1/2 PV carriers and are most likely associated with cancer worry in this population." (PMID 36767056, 2023). "Additionally, women with a pathogenic BRCA1/2 variant have reported feeling high anxiety about their result and future cancer risks, which they described as motivating information seeking and adherence to surveillance guidelines." (PMID 36556164, 2022). "However, because this is a new realm of research, additional research is needed to accurately describe the relationship between COVID-19, anxiety, and depression among at-risk cancer groups such as women with BRCA1/2 mutations." (PMID 34969949, 2021). "The identification of variants of unknown clinical significance (VUS) in the BRCA1 gene complicates genetic counselling and causes additional anxiety to carriers." (PMID 24695549, 2014). "The MICRA-J Total score was significantly associated with the status of BRCA1/2 pathogenic variant carriers and the HADS Anxiety score." (PMID 40900191, 2025). "Learning one’s BRCA1/2 carrier status is a watershed moment that can result in psychological distress, anxiety, and depression, as well as feelings of vulnerability and stigma." (PMID 39050256, 2024). "Studies examining the long-term psychological impact of bilateral mastectomy in BRCA1/2 carriers tend to show sustained reductions in anxiety and cancer-related distress following surgery." (PMID 38248108, 2024). "In this study, we identified high rates of anxiety, with over half of newly found cancer-unaffected BRCA1/2 PV carriers showing borderline clinical or clinical anxiety." (PMID 36767056, 2023).